KRTAP6-3 (keratin associated protein 6-3)
Description:
In the hair cortex, hair keratin intermediate filaments are embedded in an interfilamentous matrix, consisting of hair keratin-associated proteins (KRTAP), which are essential for the formation of a rigid and resistant hair shaft through their extensive disulfide bond cross-linking with abundant cysteine residues of hair keratins. The matrix proteins include the high-sulfur and high-glycine-tyrosine keratins.
Synonyms: KAP6.3
Tractability: No criterion of Open Targets' tractability assessment is met for any kind of drug.
Gene: Protein-coding gene on chromosome 21 (30,592,440 to 30,593,055, forward strand). Ensembl gene ENSG00000212938.
Pathways (Reactome):
Developmental Biology: Keratinization
Gene Ontology:
Molecular function: protein binding
Biological process: keratinization
Cellular component: cytosol
Genetic constraint (gnomAD): Loss-of-function variants: 7 observed, 9.08 expected, observed/expected ratio (o/e) 0.77, 90% interval 0.44 to 1.44. That is too few expected variants to judge how well the gene tolerates losing a copy. Missense variants: 121 observed, 135.29 expected, observed/expected ratio (o/e) 0.89, 90% interval 0.77 to 1.04. Synonymous variants: 62 observed, 60.58 expected, observed/expected ratio (o/e) 1.02, 90% interval 0.83 to 1.26.
Homologues: Orthologues: chimpanzee KRTAP6-3 (80% identical).
Diseases named in the same sentence as KRTAP6-3 in open-access papers:
KRTAP6-3 is named in the same sentence as 1 disease in open-access papers, as found by Europe PMC text mining. Sharing a sentence is not in itself a finding about the gene and the disease. The quoted sentences say what the papers report.
brain tumours (1 paper, 2023). "Keratin‐associated protein 6–3 (KRTAP6‐3) mutations have been found in patients with aggressive brain tumours." (PMID 36824011, 2023).